PDCD4 (programmed cell death 4)
Diseases named in the same sentence as PDCD4 in open-access papers (continued):
Sharing a sentence is not in itself a finding about the gene and the disease.
intracerebral hemorrhage (2 papers, 2022). A cerebrovascular disorder characterized by bleeding into one or both cerebral hemispheres including the basal ganglia and the cerebral cortex. "miR-340-5p targets PDCD4 to protect from a brain injury after intracerebral hemorrhage." (PMID 35415247, 2022). "Additionally, miR‐340‐5p targets PDCD4 to reduce inflammatory response and ameliorate intracerebral hemorrhage‐induced brain injury." (PMID 35957622, 2022).
laryngeal carcinoma (2 papers, 2021 to 2022). Carcinoma that arises from the laryngeal epithelium. "Since, STAT3 is enhanced in PDCD4 knockdown human laryngeal carcinoma cell line, miR-21 may be the downstream molecule of PDCD4 and metformin may inhibit miR-21 through up-regulation of PDCD4." (PMID 33849540, 2021). "Moreover, the authors suggested that miR-744-3p enhances the pro-metastatic ability of laryngeal cancer cells through programmed cell death 4 (PDCD4) and PTEN targeting, leading to the activation of matrix metallopeptidase 9 (MMP-9), which enables cancer cell migration." (PMID 35406495, 2022).
lipid metabolism disorders (2 papers, 2022 to 2025). "In addition to the role of PDCD4 in tumor progression, PDCD4 was also shown to be involved in glucose and lipid metabolism disorders, oxidative stress, inflammatory responses, and intestinal microflora imbalance." (PMID 35983977, 2022).
medulloblastoma (2 papers, 2012 to 2013). A malignant, invasive embryonal neoplasm arising from the cerebellum. "Also, miR-21 is up-regulated in medulloblastoma cells and its down-regulation increased the expression of negative modulators of cancer cell migration, E-Cadherin and TIMP2 proteins and their positive regulator PDCD4 which results in decreased motility of medulloblastoma." (PMID 23391314, 2013).
neuroblastoma (2 papers, 2020 to 2022). Neuroblastoma (NB) is the most common solid, extracranial childhood tumor. "Importantly, we confirmed that in both cortical and DRG neurons the addition of PDCD4 siRNA led to a significant decrease in PDCD4 levels detected by immunochemistry, an effect further confirmed by immunoblotting using the neuroblastoma N2a cell line, which has high transfection efficiency." (PMID 32747606, 2020).
oropharyngeal cancer (2 papers, 2016 to 2022). Carcinoma, predominantly squamous cell, arising from the epithelial cells of the oropharynx. "In oropharyngeal cancer cells, the primary inhibition of PDCD4 is facilitated by miR-21 while continuous inhibition of its expression is facilitated by miR-499." (PMID 35402235, 2022). "miR-499 and miR-21 by regulating PDCD4 could participate in the pathogenesis of oropharyngeal cancers." (PMID 35402235, 2022).
ovarian serous carcinoma (2 papers, 2022). "Through post-transcriptional suppression of the tumor suppressor gene PDCD4 (programmed cell death 4), EVs carrying miR-21 from ovarian serous carcinoma cells significantly led to malignant transformation and progression." (PMID 35159299, 2022).
pulmonary diseases (2 papers, 2017 to 2023). "Another type of PCD related to pulmonary diseases is apoptosis mediated by programmed cell death 4 (PDCD4), which encodes a tumor suppressor protein that inhibits translation initiation and promotes apoptosis." (PMID 37175715, 2023). "The molecular cascades of PTPN6/STAT3/PDCD4 play a vital role in Al2O3 NPs-involved pulmonary disorders." (PMID 29233151, 2017).
schizophrenia (2 papers, 2020 to 2021). A major psychotic disorder characterized by abnormalities in the perception or expression of reality. "Collectively, we found that the levels of Pdcd4 increased in patients with schizophrenia and MDD compared with control subjects in hippocampus, suggesting that the excessive expression of Pdcd4 might be an important factor that contributes to the development of human MDD." (PMID 32203159, 2021).
Stroke (2 papers, 2025). Sudden impairment of blood flow to a part of the brain due to occlusion or rupture of an artery to the brain. "A multitude of studies has shown that the modulation of PDCD4 can mitigate cellular damage and improve the survival rates of neuronal cells following a stroke." (PMID 39950112, 2025). "Our data suggest that αAsarone alleviates neuronal injury of stroke by facilitating neuronal autophagy through the miR-499-5p/PDCD4/ATG5 signaling pathway." (PMID 39950112, 2025).
T-cell leukemia (2 papers, 2015 to 2016). A malignant disease of the T-lymphocytes in the bone marrow, thymus, and/or blood. "PDCD4 mRNA is down-regulated by miR-21, and miR-21-mediated PDCD4 suppression is required for the survival of Notch-driven T-cell leukemia." (PMID 27542230, 2016).
T-cell lymphoma (2 papers, 2014 to 2023). "Particularly, given that both PDCD4 and PI3K/PTEN/AKT inhibit physiologically tumor promotion and progression and intravasation, their strong repression suggests that miR-21 overexpression may contribute to the typical characteristics of aggressive clinical-pathological NK/T-cell lymphoma." (PMID 25232701, 2014).
type 1 diabetes (2 papers, 2012 to 2015). "Downregulation of Pdcd4 by miR-21 has been associated with attenuation of cytotoxic effects of oxidative stress and ischemia-reperfusion in cardiomyocytes, decreasing the proinflammatory effects of TLR4 signaling, and also preventing type 1 diabetes in rodents." (PMID 22655170, 2012).
Zinc deficiency (2 papers, 2022 to 2025). A deficiency of the essential metal Zinc; an essential cofactor for many enzymes. "Studies have found that zinc deficiency increased pro-inflammatory and oncogenic miRNAs such as miR-21, miR-31, and miR-146a in esophagus and tongue tissues by suppressing tumor suppressor genes PDCD4 and PPP2R2A." (PMID 41228448, 2025).
adenomyosis (1 paper, 2022). The growth of endometrial tissue inside the muscular wall of the uterine corpus. "For example, the tumor-suppression gene programmed cell death 4 was downregulated in adenomyosis, and kisspeptin 1 is a metastasis-suppressor gene that exhibited high expression and may serve as a biomarker in adenomyosis." (PMID 35682653, 2022).
aneurysm (1 paper, 2020). Bulging or ballooning in an area of an artery secondary to arterial wall weakening. "Overexpression of miR-21 leads to downregulation of PDCD4 and PTEN inducing cell proliferation, decreasing apoptosis in the aortic wall, alleviating aneurysm expansion and protect against cell injury caused by hydrogen peroxide exposure." (PMID 32599769, 2020).
aortic stenosis (1 paper, 2020). Aortic valve stenosis is a aortic valve disease caused by the incomplete opening of the aortic valve. "For example, in patients with aortic stenosis (AS), myocardial and plasmatic miR-21 levels predicted collagen type I, collagen type III, and fibronectin expression by targeting RECK, PDCD4, and TGF-β-signaling factors." (PMID 33014530, 2020).
behavioral disorders (1 paper, 2021). "While an interfering peptide that blocked the formation of Pdcd4-eIF4A complex substantially promoted BDNF expression and corrected the behavioral disorders which were caused by CRS." (PMID 32203159, 2021). "Importantly, administration of Pdcd4 siRNA or an interfering peptide that interrupts the Pdcd4-eIF4A complex substantially promoted BDNF expression and rescued the behavioral disorders which were caused by CRS." (PMID 32203159, 2021).
benign prostatic hyperplasia (1 paper, 2015). A non-cancerous nodular enlargement of the prostate gland. "PDCD4 protein was expressed mainly in the cytoplasm, but it was also expressed to a lesser extent in the nucleus of samples of precancerous prostate and prostatic hyperplasia." (PMID 26252635, 2015).
bone tumors (1 paper, 2022). "miR-21: significantly overexpressed in different tumor types, in particular in bone tumors, it is involved in the regulation of many tumor suppressor genes and apoptosis-related proteins including tropomyosin-1 (TPM1), programmed death protein 4 (PDCD4), and metalloproteinase inhibitor 3 (TIMP3)." (PMID 35216464, 2022).
brain cancer (1 paper, 2016). A primary or metastatic malignant neoplasm affecting the brain. "Downregulation of the tumour suppressor PDCD4 is correlated with the initiation and progression of lung, colon, liver, breast, and brain cancers." (PMID 26595526, 2016). "Programmed cell death 4 (PDCD4) is a tumour suppressor protein whose expression is increased during apoptosis, and has been implicated in the development of lung, colon, liver, breast, and brain cancers." (PMID 26595526, 2016).
breast ductal carcinoma (1 paper, 2022). "PDCD4 has been found predominantly in the cytoplasm of normal breast tissue, though in the nucleus in breast ductal carcinoma, suggesting that location dictates function with PDCD4 acting as a tumour suppressor by inhibiting CAP -dependent translation in the cytoplasm in normal cells." (PMID 35847932, 2022).
CAEBV infection (1 paper, 2006). "Eventually, we found several genes with expression levels significantly higher in cell lines established from NK/T-cell lymphoma than those from CAEBV infection: FGF14, PDCD4, PCNA, MAP2K4, ITGAX and AKAP2 were preferentially expressed in SNK/T cells established from nasal NK/T lymphoma." (PMID 16449999, 2006).
chronic fatigue syndrome (1 paper, 2025). "Moreover, miR-21 is found to be upregulated in patients with chronic fatigue syndrome (CFS) and facilitates inflammatory responses by targeting PDCD4." (PMID 40626047, 2025).
emphysema (1 paper, 2017). "We hypothesize that as a consequence of suppressed expression of PTPN6, STAT3 activation and PDCD4 expression increase in airway and alveolar epithelial cells, leading to apoptosis, inflammation and emphysema in experimental COPD." (PMID 29233151, 2017).
endometrioid endometrial carcinoma (1 paper, 2021). "Similar observations showed that PDCD4 expression is associated with the histological grade of endometrioid endometrial carcinoma (EEC) where PDCD4 levels in G1 EEC tissues were higher compared with the G2/3 EEC group." (PMID 34525952, 2021).
erectile dysfunction (1 paper, 2023). Persistent or recurrent inability to achieve or to maintain an erection during sexual activity. "Inhibiting expression of PDCD4 and CCSMCs apoptosis; attenuating the erectile dysfunction." (PMID 36967787, 2023).
esophageal tumor (1 paper, 2020). "Furthermore, it has been observed that EV miR-21 stimulates invasion of esophageal tumor cells by activating the programmed cell death 4 (PDCD4)/ c-Jun NH2-terminal kinase (JNK) axis." (PMID 33080788, 2020).
experimental autoimmune encephalomyelitis (1 paper, 2023). An autoimmune demyelinating disease of the central nervous system that is produced experimentally in animals by the injection of homogenized brain or spinal cord in Freund's adjuvant. "PDCD4-deficient mice, immunized with myelin oligodendrocyte glycoprotein to induce experimental autoimmune encephalomyelitis, have shown resistance to autoimmune encephalomyelitis and developed a reduced degree of spinal cord inflammation." (PMID 36833311, 2023).
fatty liver disease (1 paper, 2025). A reversible condition wherein large vacuoles of triglyceride fat accumulate in liver cells via the process of steatosis. "Core proteins involved in SGs assembly, including G3BP1, TIA1, DDX3X, and PDCD4, have been reported to be associated with fatty liver disease." (PMID 41425091, 2025). "Notably, PDCD4 deficiency reduces stress-induced eIF2α phosphorylation and impairs SGs assembly, suggesting a protective role in fatty liver disease." (PMID 41425091, 2025).
fibrosis (1 paper, 2025). the formation of excess fibrous connective tissue in an organ or tissue in a reparative or reactive process. "We found evidence that PDCD4 may have a role in cardiac fibrosis, adding to the literature that suggests it modulates PI3K/AKT signaling to induce cardiomyocyte apoptosis." (PMID 40766329, 2025).
giant cell tumors of the (1 paper, 2021). "PDCD4 expression is also negatively correlated with Ki-67 expression in giant cell tumors of the bone, suggesting that it may suppress tumor growth." (PMID 34905503, 2021).
hepatic disorders (1 paper, 2015). "Overall, our results suggest that PIDDosome activation and consequent inhibition of the NF-κB/miR-21/PDCD4 pathway by DCA occurs both in vitro and in vivo, providing new mechanistic insights into its role as a putative pathogenic factor for hepatic disorders." (PMID 26621219, 2015).
infarction (1 paper, 2022). A localised pathological necrosis of tissue resulting from obstruction of the blood supply usually by a thrombus, an embolus, or vascular torsion. "Deficiency of PDCD4 significantly improves cardiac function, reduces infarcted tissue size, and prevents post-infarction-induced apoptosis in rats after MI." (PMID 35983977, 2022).
kidney cancer (1 paper, 2025). Primary or metastatic malignant neoplasm involving the kidney. "In the A-498 kidney cancer cell, a positive correlation (p < 0.05) was observed between miR-181a expression and the mRNA expression of FOXO1, FOXO3, PDCD4, AKT3, JNK1 and LAMTOR3." (PMID 41462911, 2025).
kidney injury (1 paper, 2018). Trauma to the kidney. "Our evidence revealed that IR increased PDCD4 and NF-κB expression and DC maturation; moreover, inhibiting miR-21 increased the effects of IR and aggravated the kidney injury." (PMID 30013485, 2018). "We conclude that miR-21 and its signaling pathways PDCD4/NF-κB are involved in IR-induced kidney injury by mediating DC maturation." (PMID 30013485, 2018).
latent infection (1 paper, 2013). "The ability to protect host cells from apoptosis is essential for EBV to establish its persistent latent infection, and therefore PDCD4 and Fas-L are usually the key target genes regulated by EBV in latency (indicated by dashed lines)." (PMID 24194922, 2013).
leiomyoma (1 paper, 2021). A well-circumscribed benign smooth muscle neoplasm characterized by the presence of spindle cells with cigar-shaped nuclei, interlacing fascicles, and a whorled pattern. "Furthermore, both FOXO3 and PDCD4 are increased in leiomyoma compared with myometrial tissue." (PMID 33575847, 2021).
Lewis lung carcinoma (1 paper, 2022). "The miR-21a in exosomes from Lewis lung carcinoma cells accelerates tumor growth through targeting programmed cell death protein 4 (PDCD4) through activating the autocrine production of IL-6 and phosphorylation of the STAT3 signaling pathway and thus enhances the expansion of MDSCs and tumor growth." (PMID 35634311, 2022).
lung tumor (1 paper, 2018). "Furthermore, expression levels of the downstream markers of the corresponding microRNAs, namely PTEN, MARCKs, TPM-1, PDCD4, SPRY-2, ETS-1, ZEB-2, FGFRL-1, EFNA-3, and k-RAS were downregulated in the lung tumor lesions of patients with the underlying condition compared to non-COPD patients." (PMID 29371906, 2018).
malignant skin tumor (1 paper, 2014). "In a mouse cancer model, PDCD4 suppressed benign and malignant skin tumor formation and progression." (PMID 24959246, 2014).
medullary thyroid cancer (1 paper, 2025). "The decrease in miR-21 levels suggests interference with the PDCD4/miR-21 pathway, which is known to influence medullary thyroid cancer progression." (PMID 38689139, 2025).
metastatic cancer (1 paper, 2015). A carcinoma which has spread from the original site of growth to another anatomic site. "Among the seven members of the miR-17~92 cluster, the guide strand miR-17-5p is predominantly responsible for promoting migration and invasion of metastatic cancer cells, targeting the mRNAs of tumor suppressor genes, such as PDCD4 (programmed cell death 4) and PTEN (phosphatase and tensin homolog)." (PMID 26629823, 2015).
metastatic melanoma (1 paper, 2021). A melanoma that has spread from its primary site to another anatomic site. "PDCD4 expression is strongly correlated between tumor and stroma of primary and metastatic melanomas, where it is associated with increased immune infiltration." (PMID 33801444, 2021). "PDCD4 is thus associated with T cell infiltration, particularly in metastatic melanoma." (PMID 33801444, 2021). "We therefore sought to further evaluate the prognostic role of PDCD4 by studying its expression levels in our large primary and metastatic melanoma TMA with relationship to clinicopathological data." (PMID 33801444, 2021). "There was a strong correlation between stroma and tumor compartment PDCD4 expression in both primary (R2 = 0.60, p < 0.0001) and metastatic melanomas (R2 = 0.73, p < 0.0001)." (PMID 33801444, 2021). "We next sought to study stromal PDCD4 expression in primary and metastatic melanoma, its correlation with total and nuclear tumor PDCD4 levels, and its association with survival." (PMID 33801444, 2021). "Our previously reported data on PLEKHA5 as a regulator of metastatic melanoma growth indicated an inverse relationship between PLEKHA5 and PDCD4." (PMID 33801444, 2021). "High PDCD4 expression resulted in improved survival in patients with primary and intracranial but not extracranial metastatic melanoma." (PMID 33801444, 2021).
Mycobacterium avium infection (1 paper, 2024). "Prior research has indicated a decline in PDCD4 levels during Mycobacterium avium infection, a process governed by miRNA 150 in RAW macrophages." (PMID 38912807, 2024).
nasal polyps (1 paper, 2025). "PTHLH, a secreted protein, is distributed across all layers of nasal polyps, and PDCD4 is primarily localized in the cytoplasm and nucleus of glandular epithelium within nasal polyps." (PMID 40894073, 2025). "MRNA and protein levels of PTHLH and CDH3 were notably elevated in nasal polyp tissue compared to the control group, whereas PDCD4 and AR were downregulated (P < 0.05)." (PMID 40894073, 2025).
oropharyngeal squamous cell carcinoma (1 paper, 2016). "However the exact regulation of PDCD4 by multiple miRNAs in oropharyngeal squamous cell carcinoma (SCC) is not well understood." (PMID 26867589, 2016).
pharyngeal carcinoma (1 paper, 2021). "PDCD4 is considered as a tumor suppressor and is correlated with apoptosis in hypo pharyngeal carcinoma cells, which has an inverse correlation with miR-21 expression." (PMID 33849540, 2021). "A study concluded that metformin prevents cell proliferation in hypo pharyngeal carcinoma possibly via down-regulation of miR-21-5P and up-regulation of programmed cell death protein 4 (PDCD4)." (PMID 33849540, 2021).
promyelocytic leukemia (1 paper, 2016). "PDCD4 expression was induced in NB4 and HL-60 acute myelocytic leukemia (AML) cell lines, primary human promyelocytic leukemia (AML-M3) cells, and CD34+ hematopoietic progenitor cells in the presence of all-trans retinoic acid." (PMID 27852288, 2016).
prostate tumor (1 paper, 2017). "Immunohistochemistry studies showed increased levels of STAT3 and IL-6, but low levels of programmed cell death protein 4 (PDCD4), in prostate tumor epithelial cells compared to adjacent perinormal prostate epithelial cells." (PMID 28467474, 2017).
retinal degeneration (1 paper, 2021). Degeneration of the retina. "The detailed function and mechanisms of Pdcd4 in regulating photoreceptors and retinal degeneration in vivo remains to be elucidated in future studies." (PMID 33082517, 2021).
Rotavirus infection (1 paper, 2019). Infection with any of the rotaviruses. "Consistently, we found that blocking PDCD4 was capable of inhibiting rotavirus infection, which is in agreement with the effect of the eIF4F complex on rotavirus infection." (PMID 30934842, 2019).